SIRT3 (sirtuin 3)
Diseases named in the same sentence as SIRT3 in open-access papers (continued):
Sharing a sentence is not in itself a finding about the gene and the disease.
diabetic cardiomyopathy (58 papers, 2015 to 2026). Diabetic cardiomyopathy is a disorder of the heart muscle in people with diabetes. "Further evidence reveals that the inhibition of mitophagy by Mst1 is associated with SIRT3, whereas depletion of SIRT3 restores cardiac function when Mst1 is overexpressed in diabetic cardiomyopathy." (PMID 32292354, 2020). "SIRT3 deficiency can aggravate diabetic cardiomyopathy by inactivating Foxo3A-mediated mitophagy and accelerate hypertensive cardiac remodeling by impairing angiogenesis." (PMID 33014281, 2020). "Furthermore, we demonstrated that the protective roles of CD38 deficiency on diabetic cardiomyopathy were related to the inhibition of apoptosis and pyroptosis through activating Sirt3/FOXO3a signaling pathways." (PMID 37958991, 2023). "In summary, SIRT3 deficiency worsened diabetic cardiomyopathy in the mice." (PMID 36902123, 2023). "However, melatonin administration was also found to promote autophagic flux, indicated by elevated LC3II and lowered p62 expression, in a mouse model of diabetic cardiomyopathy, and this was associated with SIRT3 signaling." (PMID 33790896, 2021). "Moreover, we verified that SIRT3 deficiency exacerbated diabetic cardiomyopathy and delayed diabetic skin wound healing." (PMID 34603602, 2021). "For instance, a recent animal study showed that Sirt3 deficiency exacerbated diabetic cardiomyopathy, while Sirt3 overexpression promoted mitochondrial homeostasis and cardiomyocyte survival through induction of mitophagy and autophagy via Sirt3-Foxo3A-Parkin signaling." (PMID 32289749, 2020). "Additionally, in SIRT3 deficient mice, inhibition of the interaction between SIRT3, FOXO3a, and Parkin caused a reduction in mitophagy leading to the development of diabetic cardiomyopathy." (PMID 30131726, 2018). "Characteristically obtained from medicinal plants, alkaloids like berberine reshape lipid droplet homeostasis by modulating SIRT3-mediated lipophagy, partially alleviating cardiac lipotoxicity in diabetic cardiomyopathy." (PMID 41050400, 2025). "Sirt3, a mitochondrial deacetylase, is known to preserve mitochondrial function and suppress necroptosis in diabetic cardiomyopathy and reduce ROS via activation of SOD2 in cardiac I/R injury." (PMID 40635895, 2025). "In contrast, TFEB-mediated lysosome biogenesis has been verified only for paeonol and morroniside, while SIRT3-dependent lipophagy is presently limited to berberine in diabetic cardiomyopathy and warrants confirmation in DKD models." (PMID 41050400, 2025). "A reduction in sirtuin-3 expression is evident in animal models of metabolic syndrome, HFpEF, and diabetic cardiomyopathy, signifying the importance of sirtuin-3 in disease." (PMID 40869375, 2025). "In diabetic cardiomyopathy models, elabela exerted similar protective effects via SIRT3/Foxo3a pathway activation, leading to reductions in MDA, 4-HNE, and myocardial apoptosis." (PMID 41153690, 2025). "Sirtuin 3 (Sirt3), a mitochondrial deacetylase, has been reported to attenuate diabetic cardiomyopathy by reducing oxidative stress and inflammation-mediated necroptosis." (PMID 40635895, 2025). "Up-regulation of Sirt3 has been shown to preserve mitochondrial function and ameliorate both diabetic cardiomyopathy and myocardial I/R injury." (PMID 40635895, 2025). "It has been reported that SIRT3 participates in the remission of various diseases, including myocardial infarction, atherosclerosis, neuron ischemia, hypertrophy, and diabetic cardiomyopathy." (PMID 36691640, 2023). "Krill oil inhibits NLRP3 inflammasome activation by upregulating the expression of SIRT3 and PGC-1α and prevents the pathological injuries associated with diabetic cardiomyopathy." (PMID 37196115, 2023). "Elabela, a small endogenous peptide, is shown to protect against diabetic cardiomyopathy by inhibiting oxidative stress and apoptosis via SIRT3 mediated deacetylation of the transcription factor FOXO3a." (PMID 35369299, 2022).
diabetic cardiomyopathy (continued). "Melatonin protects diabetic cardiomyopathy through MST1/SIRT3 signaling pathway 37, while garlic protects diabetic cardiomyopathy from oxidative stress by enhancing SIRT3 activity." (PMID 35002528, 2022). "Our data suggested that NEU1 inhibition exert its protective effect against diabetic cardiomyopathy via LKB1-AMPKα-SIRT3 pathway." (PMID 35002528, 2022). "SIRT3, a member of sirtuins family, is considered an essential transcription factor in the apelin-induced protection of diabetic cardiomyopathy." (PMID 35355561, 2022). "Choline, a precursor of the neurotransmitter acetylcholine, is also known to improve diabetic cardiomyopathy through SIRT3 mediated enhancement of mitochondrial protein unfolded response, fatty acid and ketone body metabolism." (PMID 35369299, 2022). "Previous studies showed that apelin increases SIRT3 expression, improves cardiac function, and ameliorates diabetic cardiomyopathy." (PMID 35355561, 2022). "Apocynin can improve myocardial reactive oxygen species overproduction and mitochondrial function through the recovery of the SIRT3/FOXO3a pathway, thereby reducing the incidence of diabetic cardiomyopathy." (PMID 36139819, 2022). "Through SIRT3 signaling, melatonin can modulate autophagy, decrease apoptosis and alleviate mitochondrial dysfunction during diabetic cardiomyopathy in mice, and SIRT3 knockout abolishes the effect of melatonin on cardiac function." (PMID 33806509, 2021). "Apelin, an endogenous peptide ligand of the human G-protein-coupled apelin receptor, gene therapy can correct microvascular insufficiency, cardiac hypertrophy, and heart dysfunction in diabetic cardiomyopathy by endorsing SIRT3 expression." (PMID 34071497, 2021). "SIRT6 and SIRT3 maintain each other’s activity and protect the heart from developing a diabetic cardiomyopathy." (PMID 33806509, 2021). "Kanwal and colleagues reported that SIRT6 and SIRT3 restore each other’s activity and prevent the development of diabetic cardiomyopathy." (PMID 34071497, 2021). "Melatonin protects against diabetic cardiomyopathy through MST1/SIRT3 signaling, and garlic protects patients with diabetic cardiomyopathy from oxidative stress by enhancing SIRT3 activity." (PMID 29643974, 2018). "In subsequent studies, we demonstrated that overexpression of apelin improved myocardial capillary density and alleviated diabetic cardiomyopathy via SIRT3 up-regulation in db/db mice." (PMID 25782072, 2015). "Our previous study shows that apelin (APLN) increases Sirtuin 3 (Sirt3) expression and ameliorates diabetic cardiomyopathy." (PMID 25311234, 2015). "Summary of compounds that improve diabetes cardiomyopathy by targeting SIRT3." (PMID 41276460, 2025). "Moreover, DHY mitigates diabetic cardiomyopathy (DCM) by activating sirtuin 3 (SIRT3), suppressing oxidative stress and inflammatory responses, and reducing apoptosis." (PMID 40746722, 2025). "Interestingly, polysulfides upregulated and S-sulfhydrated PPARγ and sirtuin 3 (SIRT-3) in cardiomyocytes and such a mechanism was relevant for assuring a prevention of diabetic cardiomyopathy in murine model." (PMID 37569263, 2023). "Another work that has studied diabetic cardiomyopathy examined the role of SIRT3 in this disease." (PMID 36902123, 2023). "Notably, while SIRT6 and SIRT3 have a myriad of functions that provide health benefits by themselves, it has been found that SIRT6 and SIRT3 also regulate each other’s activity and protect the heart from developing diabetic cardiomyopathy." (PMID 38016059, 2023). "Furthermore, to examine SIRT3′s role in diabetic cardiomyopathy, SIRT3-KO mice and WT mice injected with STZ were analyzed." (PMID 36902123, 2023).
diabetic cardiomyopathy (continued). "In addition, APLN gene therapy can promote angiogenesis and improve the recovery of cardiac function in diabetic cardiomyopathy by up-regulating SIRT3 pathway." (PMID 35002528, 2022). "Moreover, SIRT6 and SIRT3 mutually regulate each other’s activity to protect the heart from developing diabetic cardiomyopathy." (PMID 35204314, 2022). "Their results also suggested that inhibiting mitophagy down-regulation mediated by SIRT3-FoxO3A-Parkin signaling could play a role in the pathogenesis of diabetic cardiomyopathy." (PMID 34912814, 2021). "SIRT3 knockout mice exacerbated cardiac fibrosis and diabetic cardiomyopathy." (PMID 34769322, 2021). "Moreover, SIRT3 shows a potential therapeutic role in different pathologies, including cardiovascular diseases, where a SIRT3 deficiency has been associated with necroptosis, and NLRP3 activation in a diabetic cardiomyopathy." (PMID 34677429, 2021). "Moreover, melatonin notably mitigated adverse left ventricle remodeling and alleviated cardiac dysfunction in diabetic cardiomyopathy through SIRT3 signaling." (PMID 33790896, 2021). "SIRT-3 also plays a critical role in regulating autophagy during diabetes cardiomyopathy." (PMID 30487434, 2018). "Moreover, APLN gene therapy increases angiogenesis and improves cardiac functional recovery in diabetic cardiomyopathy via upregulation of the SIRT3 pathway." (PMID 29643974, 2018). "Moreover, several studies have demonstrated that SIRT3 could activate mitophagy and subsequently alleviate mitochondrial dysfunction in senile osteoporosis, diabetic cardiomyopathy and hepatic ischemia–reperfusion." (PMID 35650472, 2022). "In addition, SIRT6 and SIRT3 interact together to protect against diabetic cardiomyopathy." (PMID 33806509, 2021). "Thus, SIRT3 can inhibit diabetic cardiomyopathy and cardiac lipotoxicity." (PMID 29643974, 2018). "Considering that the roles of SIRT3 and SIRT5 in diabetic cardiomyopathy have been validated 23, 28, we assessed the expression patterns of SIRT2 and SIRT4 in heart tissues." (PMID 39781464, 2025). "In murine models of diabetic cardiomyopathy, high-intensity treadmill running activates an FGF21/AMPK/SIRT3 cascade that phosphorylates FoxO3, stabilizes mitochondria, and limits oxidative injury." (PMID 40861274, 2025). "Synergistic cardioprotective effects of TIL and syringin in diabetic cardiomyopathy through the interaction between the TLR4/NF-κB/NLRP3 and PGC1α/SIRT3 pathways have also been documented." (PMID 39388398, 2024). "In addition, syringin has been reported to exert cardioprotective effects in diabetic cardiomyopathy through the interaction of TLR4/NF-κB/NLRP3 and PGC1a/SIRT3 pathways." (PMID 35806462, 2022). "Similarly, SIRT3 catalyzes the acetylation of Forkhead box protein O (FOXO) 3, which is upstream of Parkin-dependent mitophagy, to maintain mitochondrial homeostasis during streptozotocin-induced diabetic cardiomyopathy in vivo." (PMID 32292354, 2020).
metabolic syndrome (58 papers, 2012 to 2025). A cluster of metabolic risk factors for CARDIOVASCULAR DISEASES and TYPE 2 DIABETES MELLITUS. "Through various analytical approaches, a single nucleotide polymorphism (SNP) in the SIRT3 gene was identified as being significantly associated with increased susceptibility to metabolic syndrome." (PMID 41465170, 2025). "Due to the crucial role that SIRT3 plays in adapting to metabolic stress, reduced SIRT3 activity has also been linked with metabolic syndrome." (PMID 39157755, 2024). "A nonsynonymous SNP in the catalytic domain of SIRT3 was also associated with metabolic syndrome in patients with NAFLD." (PMID 35805129, 2022). "Patients with a loss-of-function mutation in Sirt3 have increased susceptibility to the development of the metabolic syndrome." (PMID 35409099, 2022). "The case is similar in humans: a single nucleotide polymorphism in the human SIRT3 gene reduced the enzyme activity leading to mitochondrial protein acetylation and metabolic syndrome." (PMID 33499277, 2021). "Deficiency of SIRT3, known as a mitochondrial deacetylase, is a significant cause of metabolic syndrome." (PMID 33669988, 2021). "Conversely, decreased SIRT3 activity promotes the appearance of age-associated pathologies: mice lacking SIRT3 develop diseases characteristic of aging (e.g., metabolic syndrome, liver, lung and hearth fibrosis)." (PMID 34829803, 2021). "Mutations in SirT3 in mice result in defects in many of the same processes implicated in aging, such as increased incidence of cancer, cardiovascular disease, metabolic syndrome, and neurodegenerative disease." (PMID 31290578, 2019). "The importance of SIRT3 in metabolic health has been also demonstrated in humans where a single nucleotide polymorphism in the SIRT3 gene has been associated with increased susceptibility to develop the metabolic syndrome." (PMID 31130874, 2019). "Loss of Sirt3 and dysregulation of mitochondrial protein acetylation contribute to the metabolic syndrome and NASH development." (PMID 25195642, 2014). "SIRT3-mediated deacetylation leads to increase in mitochondrial fatty acid oxidation in liver whereas its deficiency leads to metabolic syndrome like features by mitochondrial protein hyperacetylation." (PMID 23840225, 2013). "Further analyses revealed that this polymorphism leads to a mutation in the SIRT3 gene that reduces its enzymatic activity, which may explain the higher incidence of metabolic syndrome observed in individuals carrying this genetic variant." (PMID 41465170, 2025). "Furthermore, a genetic study highlighted that a polymorphism within the conserved sirtuin catalytic deacetylase domain of the SIRT3 protein was associated with metabolic syndrome in humans." (PMID 39000044, 2024). "Therefore, to determine if metabolic syndrome in mid-life is a risk factor for AD, we generated a comorbid AD mouse model by deleting Sirt3 gene globally in APP/PS1 mice, an Alzheimer’s transgenic mouse model with amyloid pathology." (PMID 36396721, 2022). "The genetic polymorphisms that upregulate SIRT3 activity are associated with increased human longevity; conversely, a SIRT3 mutation that decreases its activity is correlated with a high risk of developing metabolic syndrome." (PMID 34829803, 2021). "SIRT3 deficiency has been shown to accelerate the development of Metabolic Syndrome (MetS)." (PMID 33806509, 2021). "The observations of this study suggest that SIRT3 deficiency-induced brain mitochondrial dysfunction and neuroinflammation in metabolic syndrome may play a role in late-life cognitive decline." (PMID 30510203, 2018). "A SNP rs11246020 (NC_000011.10:g.233067C>T) in the human SIRT3 gene, a nonsynonymous point mutation (V208I) which reduces its enzymatic activity, may enhance the susceptibility to metabolic syndrome." (PMID 27078640, 2016). "Sirt3 deficiency has been reported to accelerate the development of the metabolic syndrome." (PMID 24370889, 2014).
metabolic syndrome (continued). "In a recent study, Sirt3 deficiency and the accompanying mitochondrial protein hyperacetylation were reported to be associated with the development of the metabolic syndrome, a cluster of hallmark risk factors for atherosclerosis, including dyslipidemia, glucose intolerance, and central obesity." (PMID 24370889, 2014). "Sirt3 deficiency in Sirt3-KO mice is associated with accelerated development of metabolic syndrome." (PMID 24475249, 2014). "Their observations demonstrate that the SIRT3-V208I mutation reduced 34% catalytic efficiency and could increase susceptibility to developing the metabolic syndrome." (PMID 23800187, 2013). "Interestingly, it has been reported that genetic polymorphism in the SIRT3 gene is linked to longevity and metabolic syndrome." (PMID 23800187, 2013). "In addition, loss of hepatic SIRT3 contributes to the development of the metabolic syndrome at the whole organism level, as shown in animal models, highlighting SIRT3 as a potentially relevant factor not only for liver function but also in the acceleration of systemic aging processes." (PMID 41465170, 2025). "Moreover, it was shown that SIRT3 deficiency accelerates the development of metabolic syndrome." (PMID 32961898, 2020). "Sirt3 may also play a role in this induction as this factor is known to activate enzymes of fatty acid oxidation and ketogenesis, and is implicated in the metabolic syndrome." (PMID 25102070, 2014). "Knockout of SIRT3 resulted in a significantly increased hyperacetylation of mitochondrial proteins, accompanied by accelerated metabolic syndrome due to increased mitochondrial oxidative stress." (PMID 41148848, 2025). "Relevant studies have shown that the downregulation of SIRT3 is a key pathological factor of metabolic syndrome." (PMID 37659035, 2024). "Conversely, another study indicated reduced SIRT3 during skeletal muscle fasting, contrasting with reports of decreased SIRT3 in high-fat-fed rodents and humans with metabolic syndrome." (PMID 39410930, 2024). "The downregulation of SIRT3 is a key component of metabolic syndrome, a precondition for obesity and diabetes." (PMID 36677011, 2023). "The SIRT3 knockout in mice led to the development of fatty liver disease and metabolic syndrome due to the excessive acetylation of multiple mitochondrial proteins." (PMID 36978847, 2023). "In a genetic model of metabolic syndrome, Sirt3−/− mice fed a western diet had impaired brain mitochondrial respiration, lower levels of mitochondrial fission proteins Mfn1 and Mfn2, and hyperacetylated brain mitochondrial proteins." (PMID 36677011, 2023). "SIRT3 knockout mice exhibited an exacerbated metabolic syndrome, disturbed gut microbial balance, and impaired intestinal permeability." (PMID 36678226, 2023). "Through acetylome analysis, SIRT3's deacetylation of brain mitochondrial proteins can also alleviate CD induced by metabolic syndrome (MetS)." (PMID 36374406, 2023). "A recent study linked SIRT3 deficiency to neuroinflammation, which is characterized by elevated expression of IL-1β, TNF-α, and Cox-2 in SIRT3-/- mice at 8 months of age with amyloid pathology and metabolic syndrome." (PMID 37196115, 2023). "Disruption of SIRT3 function in mice, either by genetic ablation or during high-fat feeding, has been reported to display metabolic syndrome and Sirt3 knockout mice were documented to exhibit NASH." (PMID 36612019, 2022). "An analysis of 29 severely obese patients associated with metabolic syndrome found that weight loss resulted in the activation of SIRT1, SIRT3, and SIRT6 expression in hepatic and adipose tissue." (PMID 35805129, 2022). "Employing SIRT3 KO in a murine model of metabolic syndrome revealed that greater than 90% of SIRT3 KO mice developed HCC, providing an association with SIRT3 activity, metabolic syndrome, mitochondrial protein acetylation, and cancer progression." (PMID 35805129, 2022).